TTC7A (tetratricopeptide repeat domain 7A)
Description:
Component of a complex required to localize phosphatidylinositol 4-kinase (PI4K) to the plasma membrane. The complex acts as a regulator of phosphatidylinositol 4-phosphate (PtdIns(4)P) synthesis (Probable). In the complex, plays a central role in bridging PI4KA to EFR3B and HYCC1, via direct interactions (By similarity).
Synonyms: KIAA1140; TTC7; GIDID; MINAT
Tractability: Antibody: UniProt places it where antibodies can reach, with medium confidence; its Gene Ontology location is reachable by antibodies, with medium confidence. PROTAC: ubiquitination databases record sites on it; its protein half-life has been measured.
Gene: Protein-coding gene on chromosome 2 (46,915,869 to 47,076,137, forward strand). Ensembl gene ENSG00000068724.
Subcellular location: Cytoplasm; Cell membrane
Gene Ontology:
Molecular function: protein binding
Biological process: protein localization to plasma membrane; phosphatidylinositol phosphate biosynthetic process
Cellular component: cytoplasm; plasma membrane
Genetic constraint (gnomAD): Loss-of-function variants: 105 observed, 103.07 expected, observed/expected ratio (o/e) 1.02, 90% interval 0.87 to 1.2. The upper end of that interval is the gene's LOEUF score, 1.2, which puts it in group 5 of 6, group 1 being the genes least tolerant of losing a copy. Missense variants: 1,327 observed, 1,124.5 expected, observed/expected ratio (o/e) 1.18, 90% interval 1.13 to 1.24. Synonymous variants: 520 observed, 471.43 expected, observed/expected ratio (o/e) 1.1, 90% interval 1.03 to 1.19.
Gene-disease validity (ClinGen):
ClinGen rates the evidence that TTC7A causes each of these diseases.
multiple intestinal atresia (autosomal recessive): Definitive. A rare form of intestinal atresia characterized by the presence of numerous atresic segments in the small bowel (duodenum) or large bowel and leading to symptoms of intestinal obstruction: vomiting, abdominal bloating and inability to pass meconium in newborns.
Homologues: Orthologues: chimpanzee TTC7A (99% identical), macaque TTC7A (98% identical), pig TTC7A (93% identical), dog TTC7A (93% identical), rabbit TTC7A (91% identical), guinea pig TTC7A (90% identical), mouse Ttc7 (88% identical), rat Ttc7a (88% identical), tropical clawed frog ttc7a (67% identical), zebrafish ttc7a (52% identical), Caenorhabditis elegans ttc-7 (28% identical). Paralogues in human: TTC7B (50% identical), CFAP70 (14% identical), IFT88 (12% identical), TTC6 (12% identical), TMTC2 (12% identical), TMTC1 (12% identical), TTC34 (12% identical), TMTC4 (11% identical), OGT (11% identical), TTC16 (10% identical), TMTC3 (10% identical), BBS4 (9% identical), and 2 more.
Diseases named in the same sentence as TTC7A in open-access papers:
TTC7A is named in the same sentence as 32 diseases in open-access papers, as found by Europe PMC text mining. Sharing a sentence is not in itself a finding about the gene and the disease. The quoted sentences say what the papers report.
Immunodeficiency (11 papers, 2018 to 2024). Failure of the immune system to protect the body adequately from infection, due to the absence or insufficiency of some component process or substance. "Multiple intestinal atresia, early bowel inflammation and severe combined immunodeficiency have been found associated to tetratricopeptide repeat domain 7A mutations." (PMID 33673586, 2021). "Rare autosomal-recessive variants in tetratricopeptide repeat domain 7A (TTC7A) have been shown to cause intestinal and immune disorders of variable severity." (PMID 34975848, 2021). "TTC7A-deficiency is characterized by apoptotic colitis in milder cases with severe intestinal atresia and immunodeficiency in cases with complete loss of protein." (PMID 33122718, 2020). "The RNA expression of Ttc7a is relatively similar in many tissues, and studies have shown that patients with Ttc7a mutations have a phenotype specifically associated with intestinal and immune dysfunctions." (PMID 38533208, 2024). "However, a mutation in the Tetratricopeptide Repeat Domain 7A (TTC7A) gene has been associated with intestinal atresia combined with immunodeficiency." (PMID 35669397, 2022). "Mutations in the tetratricopeptide repeat domain 7A (TTC7A) gene cause very early onset inflammatory bowel diseases (VOIBD) or multiple intestinal atresia associated with immune deficiency of various severities, ranging from combined immune deficiency to mild lymphopenia." (PMID 31787977, 2019). "Enteropathy has been reported together with immunodeficiency, autoimmunity, and alopecia as a result of thymic stromal malfunction in patients with tetratricopeptide repeat domain 7A (TTC7A) defects." (PMID 37235056, 2023). "Rare autosomal-recessive variants in tetratricopeptide repeat domain 7A (TTC7A) gene have been shown to cause intestinal and immune disorders of variable severity." (PMID 34975848, 2021). "In humans, biallelic loss-of-function mutations in tetratricopeptide repeat domain 7A (TTC7A) have been shown to cause intestinal and immune disorders of variable severity." (PMID 31787977, 2019). "A loss-of-function mutation in tetratricopeptide repeat domain 7A (TTC7A) is a recently identified cause of human intestinal and immune disorders." (PMID 30455981, 2018). "The tetratricopeptide repeat domain 7A (TTC7A) gene is causative of hereditary multiple intestinal atresia (HMIA), a rare cause of intestinal obstruction associated with a profound combined immune deficiency." (PMID 30443250, 2018). "To date, TTC7A- and PI4KIIIα-related GIDID1 and GIDID2 are untreatable disorders in which surgical intervention could improve intestinal atresia without affecting the immunodeficiency outcome." (PMID 36341355, 2022).
multiple intestinal atresia (6 papers, 2018 to 2023). "More recently, mutations in tetratricopeptide repeat domain-7A (TTC7A) gene were identified from patients of very early onset IBD (VEO-IBD) or multiple intestinal atresia (MIA), which result in reduced cell adhesion, elevated apoptosis, defective epithelial barrier and polarity." (PMID 29980668, 2018).
combined immunodeficiency (4 papers, 2021 to 2025). A broad classification of inherited disorders presenting at birth that affect both the cell-mediated and humoral aspects of the immune response. "Mutations in TTC7A have been associated with the rare hereditary human disease, combined immunodeficiency with multiple intestinal atresias (CID-MIA)." (PMID 40136694, 2025). "The majority had no specific past medical history, except for one with esophageal atresia (EA) and the other with combined immunodeficiency multiple intestinal atresias (CID-MIA) due to TTC7A (tetratricopeptide repeat domain 7A) mutation." (PMID 34970514, 2021). "Approximately 50 cases of TTC7A deficiency have been reported worldwide, most of which are MIA with combined immunodeficiency (CID), and only a few are IBD cases." (PMID 35783276, 2022).
inflammatory bowel disease (3 papers, 2018 to 2022). A spectrum of small and large bowel inflammatory diseases of unknown etiology. "Gene expression analysis reveals that barrier-function-related inflammatory bowel disease (IBD) susceptibility genes (e-cadherin, hnf4a, ttc7a) are suppressed, while inflammatory response genes are stimulated in the mutants." (PMID 29980668, 2018).
severe combined immunodeficiency (3 papers, 2019 to 2022). Severe combined immunodeficiency (SCID) comprises a group of rare monogenic primary immunodeficiency disorders characterized by a lack of functional peripheral T lymphocytes resulting in early-onset severe respiratory infections and failure to thrive. "TTC7A deficiency can present in the neonatal period with intestinal atresia, apoptotic enterocolitis, and severe combined immunodeficiency (SCID)." (PMID 34122435, 2021).
immune deficiency disorders (2 papers, 2021 to 2022). "Neonatal or infantile-onset IBD is often associated with primary immune deficiency disorders, especially those caused by mutations in IL-10, XIAP, NCF2, IPEX, and TTC7A." (PMID 35783276, 2022).
ciliopathies (1 paper, 2019). "We prioritized TTC28 because variants in TTC7A (OMIM: 609332), a member of the same gene family, causes autosomal recessive gastrointestinal defects, and variants in TTC21B (OMIM: 612014) are reported in human ciliopathies." (PMID 30679815, 2019).
colitis (1 paper, 2020). Inflammation of the colon. "Together this implicates UBR5 in regulating TTC7A signaling in VEOIBD patients with apoptotic colitis." (PMID 33122718, 2020).
colon cancer (1 paper, 2025). "Interestingly, siRNA-mediated knockdown of TTC7A also increased the TRm6A levels in colon cancer cell lines." (PMID 39897037, 2025).
ectodermal dysplasia (1 paper, 2025). "In addition, genes such as TTC7A, SKIV2L, TTC37, and DKC1 also play a role in epithelial maintenance, with their defects often leading to ectodermal dysplasia, dysmorphism, and intestinal epithelial damage." (PMID 40474095, 2025).
Meconium ileus (1 paper, 2021). Obstruction of the intestine due to abnormally thick meconium. "Immunohistochemical staining of paraffin slice confirmed a reduced level of TTC7A expression in patient ileum tissue compared with that from meconium ileus patient as control." (PMID 34975848, 2021).
intestinal disorder (4 papers, 2018 to 2022). A non-neoplastic or neoplastic disorder that affects the small or large intestine. "As TTC7A is known to interact with PI4KIIIa, leflunomide might also be effective in patients with PI4KIIIa deficiency suffering from intestinal disorders." (PMID 36341355, 2022). "Recently, we and others reported that recessive loss-of-function mutations in the gene coding for tetratricopeptide repeat domain 7A (TTC7A) lead to immune and intestinal disorders of highly variable severity." (PMID 30455981, 2018). "Unfortunately, there is no standard treatment for TTC7A-deficiency and traditional therapies do little to treat the intestinal disease (MIA and VEO-IBD)." (PMID 34975848, 2021).
cancer (2 papers, 2024 to 2025). A tumor composed of atypical neoplastic, often pleomorphic cells that invade other tissues. "We found that the mRNA level of TTC7A is inversely and significantly associated with that of TTC7B in human cancer cell lines according to CCLE datasets (n=1037; r=-0.41)." (PMID 39897037, 2025).
gastrointestinal disease (1 paper, 2024). A disease that occurs in the gastrointestinal system, excluding the hepatobiliary system. "Loss-of-function mutations in the gene encoding tetratricopeptide repeat domain 7A (TTC7A) cause severe infantile-onset gastrointestinal disease, characterized by profound epithelial architecture defects and overall epithelial dysfunction." (PMID 39495812, 2024).
TTC7A also shares sentences with these, for which no sentence is quoted: chronic granulomatous disease (3 papers); intestinal atresia (3); prostate carcinoma (3); bone tumor (2); Enteropathy (2); alopecia (1); Autoimmunity (1); breast carcinoma (1); Chronic Intestinal Pseudo-Obstruction (1); common variable immunodeficiency (1); Esophageal atresia (1); hereditary multiple intestinal atresia (1); intestinal inflammation (1); intestinal obstruction (1); leukemia (1); lymphopenia (1); lymphoproliferative syndrome (1); pancreatic adenocarcinoma (1).